NUBP2 (NUBP iron-sulfur cluster assembly factor 2, cytosolic)
Description:
Component of the cytosolic iron-sulfur (Fe/S) protein assembly (CIA) machinery. Required for maturation of extramitochondrial Fe-S proteins. The NUBP1-NUBP2 heterotetramer forms a Fe-S scaffold complex, mediating the de novo assembly of an Fe-S cluster and its transfer to target apoproteins. Negatively regulates cilium formation and structure.
Synonyms: NBP 2; CFD1; CIAO6
Tractability: PROTAC: ubiquitination databases record sites on it; its protein half-life has been measured.
Gene: Protein-coding gene on chromosome 16 (1,782,932 to 1,789,189, forward strand). Ensembl gene ENSG00000095906.
Subcellular location: Nucleus; Cytoplasm, cytoskeleton, microtubule organizing center, centrosome; Cytoplasm; Cytoplasm, cytoskeleton, cilium axoneme; Cytoplasm, cytoskeleton, microtubule organizing center, centrosome, centriole; Cytoplasm, cytoskeleton, microtubule organizing center
Subcellular location (Human Protein Atlas): Cytosol; Nucleoplasm
Pathways (Reactome):
Metabolism: Cytosolic iron-sulfur cluster assembly
Gene Ontology:
Molecular function: protein binding; nucleotide binding; 4 iron, 4 sulfur cluster binding; ATP binding; ATP-dependent FeS chaperone activity; iron-sulfur cluster binding
Biological process: iron-sulfur cluster assembly
Cellular component: cytoplasm; cytosol; iron-sulfur cluster assembly complex; axoneme; centriole; centrosome; microtubule organizing center; nucleus; spindle pole centrosome
Genetic constraint (gnomAD): Loss-of-function variants: 23 observed, 22.35 expected, observed/expected ratio (o/e) 1.03, 90% interval 0.74 to 1.46. The upper end of that interval is the gene's LOEUF score, 1.46, which puts it in group 6 of 6, group 1 being the genes least tolerant of losing a copy. Missense variants: 403 observed, 368.26 expected, observed/expected ratio (o/e) 1.09, 90% interval 1.01 to 1.19. Synonymous variants: 186 observed, 163.18 expected, observed/expected ratio (o/e) 1.14, 90% interval 1.01 to 1.29.
Homologues: Orthologues: guinea pig NUBP2 (86% identical), dog NUBP2 (85% identical), mouse Nubp2 (84% identical), rat Nubp2 (84% identical), macaque NUBP2 (79% identical), tropical clawed frog nubp2 (76% identical), zebrafish nubp2 (67% identical), chimpanzee NUBP2 (66% identical), pig NUBP2 (66% identical), Drosophila melanogaster Nubp2 (51% identical). Paralogues in human: NUBP1 (50% identical), NUBPL (35% identical).
Diseases named in the same sentence as NUBP2 in open-access papers:
NUBP2 is named in the same sentence as 10 diseases in open-access papers, as found by Europe PMC text mining. Sharing a sentence is not in itself a finding about the gene and the disease. The quoted sentences say what the papers report.
oral squamous cell carcinoma (2 papers, 2023 to 2025). "It has been discovered that the production of long splicing isoform of NUBP2 suppressed cancer cell proliferation in oral squamous cell carcinoma." (PMID 38492158, 2025).
head and neck cancer (1 paper, 2023). A primary or metastatic malignant neoplasm affecting the head and neck. "Since NUBP2 is one of the major cytosolic components of the Fe/S cluster assembly and is relatively less characterized, we sought to analyze the expression of other components of the cytosolic and nuclear Fe/S cluster assembly in oral cancer and TCGA head and neck cancer data." (PMID 37810966, 2023).
lung carcinoma (1 paper, 2023). "Indeed, RT–PCR results indicated that the deletion of MEN1 in lung cancer cells increased the instances of short splicing isoforms in the FAM189B, NUBP2, ENDOV and TARBP2 genes, but inhibited generation of the CPSF7, MRRF and LETMD1 splicing isoforms." (PMID 37395406, 2023).
lymph node metastasis (1 paper, 2023). "Although a large majority of OSCC cases (72%) showed positive staining, NUBP2 positivity did not significantly correlate with patient age, gender, tumor site, tumor size, or lymph node metastasis." (PMID 37810966, 2023).
cancer (5 papers, 2013 to 2025). A tumor composed of atypical neoplastic, often pleomorphic cells that invade other tissues. "Nucleotide binding protein 2 (NUBP2) plays a vital role in the assembly of cytosolic Fe/S protein and has been implicated in cancer progression." (PMID 38492158, 2025). "Aberrant NUBP2 expression has also been observed in several cancers, including gastric cancer and hepatocellular carcinoma." (PMID 38492158, 2025). "Subsequently, we verified the expression of NUBP2 in CRC tumor tissues and para-carcinoma tissues using IHC staining, and further investigated its association with clinicopathological parameters." (PMID 38492158, 2025). "Here, higher expression of NUBP2 was observed in CRC tissues and cell lines compared to para-carcinoma tissues and normal cells, and this elevated expression was associated with increased tumor malignancy." (PMID 38492158, 2025). "The expression of NUBP2, PLCB3, PPP1CA, TBCB, and UBE2C were positively correlated with PPP1R14B in the majority of cancer types." (PMID 34858479, 2021).
tumor (3 papers, 2022 to 2025). "Correspondingly, animal xenografts demonstrated that loss of NUBP2 resulted in a decreased tumor growth in vivo." (PMID 38492158, 2025). "The tumor growth curves revealed that NUBP2 knockdown significantly retarded the growth of CRC tumors in mice compared to the mice of shCtrl group." (PMID 38492158, 2025). "Collectively, these data strongly demonstrated that downregulation of NUBP2 repressed CRC tumor progress in vivo." (PMID 38492158, 2025). "By analyzing the clinicopathological data, it was revealed that the expression of NUBP2 was related to metastasis and tumor stage (P < 0.05 for both)." (PMID 38492158, 2025). "In order to assess the biological significance of NUBP2 on tumor cell proliferation, IHC staining for Ki-67 (an indicator of proliferation) were performed in tumor tissues of each group." (PMID 38492158, 2025). "Furthermore, we established a subcutaneous CRC model to evaluate the impact of NUBP2 on tumor growth in vivo." (PMID 38492158, 2025). "Additionally, the effects of NUBP2 knockdown on the tumor growth in vivo were investigated in a CRC xenograft model." (PMID 38492158, 2025). "Our results showed higher expression of NUBP2 in CRC tissues, which positively correlated with the pathological stage, indicating its involvement in tumor malignancy." (PMID 38492158, 2025). "In conclusion, our findings revealed that NUBP2 knockdown repressed malignant phenotype of CRC cells by suppressing cellular proliferation and migration while stimulating apoptosis, and inhibited tumor growth in vivo." (PMID 38492158, 2025).
NUBP2 also shares sentences with these, for which no sentence is quoted: colorectal cancer (1 paper); glioma (1); oral cancer (1); serous cystadenocarcinoma (1).